IFNG (interferon gamma)
Diseases named in the same sentence as IFNG in open-access papers (continued):
Sharing a sentence is not in itself a finding about the gene and the disease.
atherosclerosis (continued). "Interestingly, atherosclerosis is considered primarily a chronic inflammatory condition that may be influenced by leukocyte count, interferon gamma (IFN- γ), and cytokines." (PMID 37731134, 2023). "FO B cells can contribute to atherosclerosis progression, and despite the increased co-inhibitory PD-L1 expression following IFNγ exposure, we cannot exclude that a decrease in FO B cells in the adoptively transferred IFNγ-stimulated B cells also contributed to the observed anti-atherogenic effect." (PMID 35187121, 2022). "Moreover, PD-1 expressing CD8+ T cells from patients with atherosclerosis produced more anti-atherogenic IL-10 and less pro-atherogenic cytokines (IFNγ, TNFα) compared to PD-1−CD8+ T cells, further supporting a protective role for PD-1 in T cell-mediated immunity." (PMID 34790707, 2021). "Indeed, recombinant IL-18 administration to Apoe−/− mice promoted atherosclerosis development in an IFNγ-dependent manner, while its neutralization by the natural inhibitor IL-18 binding protein (IL-18BP) or genetic knockout of IL-18 significantly reduced disease progression." (PMID 33562334, 2021). "Similarly, the regulation of NOV might play a bridging role in inflammatory response and lipid accumulation in macrophages during atherogenesis as both toll-like receptor 4 and IFNγ-signaling represent major regulators in atherosclerosis." (PMID 31921150, 2019). "The actions of IFNγ have led to the hypothesis that Thelper1 (Th1)-lymphocytes may be essential for, or at least prominent contributors to, M1 polarization in vivo, a concept that has been acknowledged in papers dealing with atherosclerosis." (PMID 25389425, 2014). "Evidence that IFNγ is necessary and sufficient to cause vascular remodeling is supported by mouse models of atheroma formation, as the serological neutralization or genetic absence of IFNγ markedly reduces the extent of atherosclerosis." (PMID 25478796, 2014). "Chronic elevated levels of IL-18 may lead to a persistently increased expression of IL-18 inducible cytokines downstream of the NF-κB/AP-1 signal pathway, i.e. IFNγ and MMPs, which are of importance for an inflammatory state in atherosclerosis in general and for arterial remodeling, important in HT." (PMID 22141572, 2011). "Seven core targets-IFNG, CXCL8, TNF, TGFB1, IL2, IL4, and RELA-were identified via network pharmacology, involving key pathways such as lipid-atherosclerosis, AGE-RAGE, and IL-17 signaling." (PMID 40708520, 2026). "Given that atherosclerosis is a chronic inflammatory disorder, THP‐1 monocytes were treated with several proinflammatory cytokines (lipopolysaccharide [LPS], interferon gamma [IFN‐γ], and LPS + IFN‐γ) to mimic the in vivo inflammatory microenvironment." (PMID 41527512, 2026). "The pro-inflammatory cytokine IFNγ and TLR4 stimuli are among key factors contributing to the onset and progression of atherosclerosis." (PMID 41155497, 2025). "The key factors contributing to the early stages of atherosclerosis and plaque development include the pro-inflammatory cytokine interferon (IFN)α and IFNγ and the pattern recognition receptor (PRR) Toll-like receptor 4 (TLR4)." (PMID 39840103, 2024). "The key factors contributing to the onset and progression of atherosclerosis include the pro-inflammatory cytokines interferon (IFN)α and IFNγ and the pattern recognition receptor (PRR) Toll-like receptor 4 (TLR4)." (PMID 39840103, 2024). "Mercury exposure activates p38 MAPK and increases the expression of TNF-α and interferon gamma (IFN-γ), which promote atherosclerosis." (PMID 37396849, 2023). "In the process of atherosclerosis, inflammatory response is accompanied by the increase of many proinflammatory factors, including MCP1, interferon-gamma (IFN-γ), IL-8, VCAM1 and TNF." (PMID 35534881, 2022). "In conclusion, our data show that IFNγ-stimulated B cells strongly upregulate PD-L1, inhibit TFH cell responses and protect against atherosclerosis." (PMID 35187121, 2022).
atherosclerosis (continued). "A follow-up study by the same group reported that, in response to TNF-α and interferon gamma (IFN-γ), PRMT5-induced methylation of p65 at R174 increases the expression of CXCL11, another chemokine that worsens the atherosclerosis pathology." (PMID 34685445, 2021). "Several inflammatory and atherosclerosis-related stimuli have been shown to induce OLR1 expression, including lipopolysaccharide (LPS), TNFα, interleukin-1 (IL-1), interferon gamma (IFNγ), oxLDL, and angiotensin II." (PMID 34867460, 2021). "VitD/Dexa treatment also reduced the percentage of IFNγ+ CD8+ T cells, which have been recently suggested as promoters of atherosclerosis by controlling monopoiesis and circulating monocytes." (PMID 32395119, 2020). "T-helper-1 (Th-1) lymphocytes secrete pro-inflammatory cytokines, such as interferon-gamma (IFN-γ), IL-2 and TNF-α, which activate macrophages, endothelial cells and SMC, therefore propagating and accelerating atherosclerosis." (PMID 31357404, 2019). "Pro-inflammatory cytokines Interferon (IFN)α, IFNγ and Toll-like receptor 4 (TLR4) activators are key factors contributing to early stages of atherosclerosis." (PMID 30283459, 2018). "Key factors contributing to onset and progression of atherosclerosis include the pro-inflammatory cytokines Interferon (IFN)α and IFNγ and the Pattern Recognition Receptor (PRR) Toll-like receptor 4 (TLR4)." (PMID 30283459, 2018). "Key factors contributing to early stages of atherosclerosis and plaque development include the pro-inflammatory cytokines Interferon (IFN)α, IFNγ and Interleukin (IL)-6 and Toll-like receptor 4 (TLR4) stimuli." (PMID 27166190, 2016). "Our study provides evidence to suggest that in ECs and VSMCs STAT1 orchestrates a platform for cross-talk between IFNγ and TLR4, and identifies a STAT1-dependent gene signature that reflects a pro-atherogenic state in human atherosclerosis." (PMID 25478796, 2014). "Interleukin 18 (IL-18), previously known as interferon-gamma (IFN-γ) inducing factor, is a proinflammatory member of IL-1 superfamily which plays a role in the initiation and progression of atherosclerosis." (PMID 24307760, 2013). "The chronic inflammatory environment present in atherosclerosis, marked by elevated cytokines such as IL-1β, IL-6, TNF-α, and interferon-gamma (IFN-γ), promotes oxidative stress and DNA damage in HSCs, particularly given their high turnover rates required to sustain lifelong hematopoiesis." (PMID 41516113, 2025). "To investigate the clinical relevance of SPON2 in NK cells more specifically with relation to atherosclerosis, we examined SPON2 expression in pro-inflammatory carotid vs. pro-homeostatic femoral plaque tissue, in relation to IFNG and adaptive NK cell gene signature." (PMID 39941136, 2025). "IL-18 can trigger atherosclerosis-relevant IFNγ expression even in the absence of T cells, as the administration of recombinant IL-18 to lymphocyte-deficient SCID mice led to increased lesion size accompanied by elevated IFNγ levels in the circulation." (PMID 33562334, 2021). "Moreover, our data offer an explanation for the comparable effects of IFNα or IFNγ priming on TLR4-induced activation in vascular and immune cells, with important implications in atherosclerosis." (PMID 31231385, 2019). "Increased production of IFNγ in RA, as a result of a significant amount of CD4+CD28− cells that promoteTh1cell activation, could also have a critical role in accelerated atherosclerosis." (PMID 29954107, 2018). "T-cell mediated immune responses in atherosclerosis are believed to be Th1 dominated, based on evidence that IFNγ but not IL-4 is abundant in human plaques." (PMID 26886778, 2016). "The serological neutralization or genetic absence of IFNγ markedly reduces the extent of atherosclerosis." (PMID 27166190, 2016). "We hypothesize that STAT1-dependent transcriptional changes in vascular cells involved in cross-talk between IFNγ and TLR4, reflect pro-atherogenic responses in human atherosclerosis." (PMID 25478796, 2014).
atherosclerosis (continued). "This could point to the role of IFNγ and TLR4 activation in human atherosclerosis, which is in agreement with previous studies." (PMID 25478796, 2014). "It is consistent with studies showing that knockout (KO) of IFNγ and its receptors reduces atherosclerosis progression, although the impact on M1 polarization was not measured directly in any of these IFNγ KO investigations." (PMID 25389425, 2014). "Understanding how IFNγ and STAT1 signaling intersect with PU.1 and these epigenetic processes in MØ and MØ subtypes in atherosclerotic plaques could provide new insights into the molecular basis of MØ-specific STAT1-dependent transcription and its potential contribution to atherosclerosis." (PMID 40607379, 2025). "Moreover, our model offer for the first time an explanation for the comparable effects of IFNα or IFNγ priming on TLR4-induced activation in vascular and immune cells, which correlates with the important roles of both IFN types in vascular inflammation and atherosclerosis progression." (PMID 31231385, 2019). "Previously, it was shown that absence of PD-1/PD-L1/2 signaling can aggravate atherosclerosis by enhancing T cell proliferation, activation of both CD4+ as CD8+ T cells, and more specifically by increasing pro-atherogenic IFNγ production by T cells." (PMID 34790707, 2021). "Two patterns were enriched in functional GO categories (interferon-gamma-mediated signaling pathway and MHC class II antigen processing) but none of these two patterns was related to atherosclerosis after conditioning on smoking." (PMID 23372645, 2013). "In contrast, TNF, interferon regulatory factor 2 (IRF2) and interferon gamma (IFNG) were predicted to be inhibited and insulin activated in both datasets, and the computing of LARP1 activity was not possible in VAT samples from humans with atherosclerosis." (PMID 35737302, 2022).
Arthritis (270 papers, 2005 to 2026). Inflammation of a joint. "In arthritis (RA), NK cells have been identified as causative agents since their activating signals (IFNγ, cytotoxicity) exceed the inhibitory mechanisms." (PMID 39940745, 2025). "In contrast to these in vitro findings, in both models of arthritis, we observed a loss of in vivo IL-10R expression on the intestinal epithelium and an increase in IFNγ expression by leukocytes." (PMID 34296202, 2021). "Taken together, these results suggest that both arthritis-associated bacteria and inflammatory cytokines, such as IFNγ, contribute to the loss of IEC IL-10R expression in arthritis." (PMID 34296202, 2021). "For instance, mice with a disrupted IFNγ gene are susceptible to experimental autoimmune encephalomyelitis whereas collagen-induced arthritis is worsened in IFNγ receptor-deficient mice." (PMID 28954232, 2017). "Finnegan and colleagues demonstrated that in contrast to CIA, IFNγ deficiency or treatment with anti-IFNγ antibody resulted in the amelioration of arthritis." (PMID 26903711, 2016). "We would anticipate that p35−/− mice are susceptible to developing arthritis induced by s.c. immunization similar to IFNγ−/− mice." (PMID 25253467, 2014). "Of the TH1 responses, IFNγ in particular has been associated with protection from disease in experimental models of arthritis." (PMID 22691272, 2012). "The IFNγ: IL-4 ratio shifted toward the Th1 direction in the older, arthritis-susceptible mice, while in the arthritis-resistant 1-month-old group these two signature cytokines were produced in approximately equal amounts." (PMID 19519881, 2009). "Next, we investigated whether the loss of IL-10R expression by IECs could be a consequence of arthritis-related dysbiosis and/or the result of the elevated IFNγ expressed by intra-epithelial lymphocytes (IELs) and lamina propria mononuclear cells (LPMCs)." (PMID 34296202, 2021). "Likewise, but at transcriptome level, in autoantibody-positive arthralgia patients, risk factors for progression to arthritis were reported to be involved in cytokine- and chemokine-mediated immunity, including low levels of IFNG and IL-7R." (PMID 33168080, 2020). "Interestingly, a recent report also demonstrated that TOFA attenuates arthritis manifestations and reduces the pathogenic IFNγ+CD4+ splenic T cells in adjuvant arthritis rats." (PMID 28830352, 2017). "Interestingly, in proteoglycan-induced arthritis, mice deficient in IL-4Rα showed higher IL-1β, IL-6 and MIP1a, whereas levels of IFNγ and autoantibodies were less affected." (PMID 23092393, 2012). "While IFNγ-deficient BALB/c mice developed less severe arthritis, IL-4-/- mice in the same background aggravated the response to PG immunization: an earlier onset with more severe inflammation was detected when compared to age- and gender-matched wild-type mice." (PMID 19519881, 2009). "These morphological changes were matched by an infiltration of IFNγ-expressing inflammatory leukocytes and a loss of anti-inflammatory IL-10-expressing cells, supporting previous preliminary human studies suggesting that the gut is a site of leukocyte infiltration during arthritis." (PMID 34296202, 2021). "In general, from studies using human patient data and animal models of alphaviral arthritis, acute alphaviral-induced arthritis is hallmarked by increased levels of IFNα/β, IFNγ, TNFα, IL-6, IL-1, IP-10, IL-12, IL-15 and CXCL9MCP-1 (CCL2), and MIF-I." (PMID 41442410, 2026). "We also determined the concentrations of the cytokines IL-6, IL-10, IFNγ, TNFα, IL-17A, IL-17F, and IL-22 in serum samples of the arthritis patients." (PMID 40806470, 2025). "In conclusion, our study shows that blood levels of insulin combined with age, RA classification score, and IFNg were predictive of MTX response in early treatment-naïve arthritis patients." (PMID 40643485, 2025).
Arthritis (continued). "Irmler and collaborators in 2007 showed that IFNγ-/- AIA mice presented an increased inflammatory response, and treatment with the recombinant murine IFNγ into the knee joint during arthritis inducing was capable to attenuate the joint injury." (PMID 38691538, 2024). "In smoking SLE patients, there were prevalent malar rash, mucosal ulcers, arthritis, and Raynaud’s phenomenon, elevated usage of prednisone and hydroxychloroquine, and reduced serum levels of IFNγ." (PMID 38164134, 2023). "Consistent with flow cytometry data, serum IFNγ was significantly reduced after the treatment of arthritis." (PMID 35413951, 2022). "In vivo, in a murine model of collagen-induced arthritis, IL-27 induced Th1 differentiation and IFNγ secretion constraining osteoclast differentiation." (PMID 35479090, 2022). "We show that exposing intestinal organoids to IFNγ reduces IL-10R expression by epithelial cells and that mice lacking epithelial IL-10R display increased intestinal permeability and exacerbated arthritis." (PMID 34296202, 2021). "Mice that received AAV8.CII prophylaxis had an approximate 50% reduction in the OD of pro-inflammatory IFNγ and a concomitant 2.5-fold increase in IL-10 level when compared to arthritis controls." (PMID 34521922, 2021). "Upon AIA induction, Cl8−/− mice develop a significantly exacerbated arthritis compared to WT controls and a rise in the frequencies of IFNγ+ and IL-17+CD45+ cells in the spleen." (PMID 34296202, 2021). "Following the acute phase, patients who recovered from CHIKV and patients with chronic CHIKV-induced arthritis both had roughly equal frequencies of CHIKV-specific IFNγ-producing T cells." (PMID 31736977, 2019). "Dietary palmitic acid, an inducer of ER stress and RIDD in NKT cells, and tunicamycin, an activator of ER stress and UPR, inhibit IL-4 and IFNγ in a mouse model of arthritis and leading to reduced antibody induced-joint inflammation." (PMID 30978945, 2019). "Ninety-six days after arthritis induction, spleens and lymph nodes of WT and Ptpn22−/− mice were pooled and assessed for IFNγ+ CD4+ T-cells." (PMID 30054208, 2018). "It has been reported that Th17 cells in the gut of patients with Crohn’s disease or in the joints of those with arthritis co-express IL-17 and interferon-gamma (IFN-γ)." (PMID 29892286, 2018). "The inflammatory cytokines TNFα, IFNγ, IL-6 and IL-17 have been shown to play crucial roles in the development of arthritis in the K/BxN model." (PMID 28882929, 2017). "Although generally considered a proinflammatory cytokine, IFNγ has been assigned a protective role in the pathogenesis of arthritis, with genetic disruption of IFNγ resulting in increased disease activity." (PMID 27488122, 2016). "Among the cytokines with the greatest importance in inflammatory responses, pain and arthritis, we selected nine cytokines for further study (IFNγ, TNFα, IL1, IL4, IL6, IL10, IL12, IL17 and IL23)." (PMID 26218592, 2015). "Altering the route of immunization to the s.c. route that is used in EAE, EAU, and CIA converts PGIA to IL-17-dependent arthritis where both IFNγ-producing and IL-17-producing CD4+ T cells are activated." (PMID 25253467, 2014). "It was found that in vivo neutralization of IFNγ exacerbates Th17 induced arthritis, and anti-IL-17A treatment delays onset of arthritis induction by Th17 cells." (PMID 25152827, 2014). "Studies with various KO mice or blocking antibodies have dissected the separate roles of Th1 and Th17 effector responses in the peripheral arthritis aspect of the PG-induced disease model, wherein IFNγ serves an an important regulatory role in arthritis." (PMID 22269151, 2012). "The remaining arthritis that ensues independently of IFNγ is further reduced as a consequence of IL-17 neutralization." (PMID 22269151, 2012). "In vivo, IL-17 inhibition prevented the component of PG-induced arthritis that occurs independently of IFNγ." (PMID 22269151, 2012).